CPLX1 (complexin 1)
Diseases named in the same sentence as CPLX1 in open-access papers (continued):
Sharing a sentence is not in itself a finding about the gene and the disease.
cancer (2 papers, 2018 to 2025). A tumor composed of atypical neoplastic, often pleomorphic cells that invade other tissues. "Although CPLX1 has been implicated in the prognosis of various cancers, its therapeutic potential remains underexplored." (PMID 40703507, 2025). "Of the genes that HHV-6A sequences were found to be integrated into or located near, most were significantly associated with cancers, and six, including CPLX1, IGFBP3, and the oncogene SH3RF2, were associated with malignant tumor formation (p = 8.45 × 10−7)." (PMID 30542640, 2018). "For example, in a cancer-induced bone pain model, changes in CPLX1 expression were closely associated with the occurrence of pain, suggesting that CPLX1 may play an important role in the mechanism of cancer-related pain." (PMID 40703507, 2025). "Associations between CPLX1 and poor prognosis have been observed in various cancer types." (PMID 40703507, 2025). "On the one hand, some studies have pointed out that the high expression of CPLX1 is associated with the aggressiveness and poor prognosis of certain types of cancers; on the other hand, other studies have shown that it may have a tumor-suppressing effect under specific conditions." (PMID 40703507, 2025). "CPLX1 is gradually showing its importance in cancer research, and the multiple biological processes it participates in are closely related to tumorigenesis and development." (PMID 40703507, 2025). "Looking forward, the potential of CPLX1 as a new target for cancer therapy is worth looking forward to." (PMID 40703507, 2025). "Such dataset outcomes imply that CPLX1 could be a prognostic biomarker within numerous cancers, including CRC." (PMID 40703507, 2025). "Studies have shown that CPLX1 may influence the behavior of tumor cells in the cancer microenvironment and participate in tumorigenesis and progression." (PMID 40703507, 2025). "Therefore, future studies need to explore more systematically and in depth the specific mechanisms of CPLX1 in different tumor types and different microenvironments in order to better understand its dual roles in cancer." (PMID 40703507, 2025). "In recent years, the relationship between CPLX1 and cancer has been gradually emphasized." (PMID 40703507, 2025). "In addition, CPLX1 may serve as a biomarker in certain types of cancer, providing new ideas for early diagnosis and prognostic assessment of cancer." (PMID 40703507, 2025). "However, there is still some controversy about the role of CPLX1 in different types of cancer." (PMID 40703507, 2025). "By employing advanced statistical analyses, including Kaplan-Meier survival plots and Cox regression models, this study aims to provide insights into the prognostic significance of CPLX1 in CRC, thereby contributing to the understanding of its role in cancer biology and treatment resistance." (PMID 40703507, 2025).
infection (2 papers, 2020 to 2025). The state of being infected such as from the introduction of a foreign agent such as serum, vaccine, antigenic substance or organism. "MA10 infection induced seven additional down-regulated (Hsp90aa1, Tcf7l2, Gnas, Sparcl1, Ywhag, Cpe, Sparc) and four upregulated DEGs (Ppp1r1b, Penk, Arpp21, Pcp4), whereas Aβ pathology resulted in five down-regulated (Cplx1, Syp, Meg3, Snhg11, Penk) and one upregulated DEG (Psen1)." (PMID 41497643, 2025).
tumor (1 paper, 2025). "Our findings thus suggest that elevated levels of CPLX1 are closely associated with mechanisms promoting immune escape in CRC tumor cells, thus contributing to both tumor growth and progression." (PMID 40703507, 2025). "This investigation revealed that CPLX1 levels within tumor samples were markedly associated with tumor status and pathological phase, as well as survival outcomes." (PMID 40703507, 2025). "CPLX1 levels were also identified as positively linked to the levels of NK cells and TReg, suggesting that it may affect the composition of the tumor microenvironment through various mechanisms." (PMID 40703507, 2025). "Its processing revealed that CPLX1 was significantly higher expressed in tumor tissues than in the normal group, and subsequent fractionation revealed its increased immune cell infiltration in tumor tissues." (PMID 40703507, 2025). "Here, we identified an association between infiltration and CPLX1 levels, observing that CPLX1 was negatively associated with the numbers of both Tcm and T helper cells in CRC tumor samples." (PMID 40703507, 2025). "The first step undertaken was surveying the levels of CPLX1 in tumor and control samples using TIMER2.0." (PMID 40703507, 2025). "A further comparison of paired CRC and normal tissues confirmed these findings, showing elevation of CPLX1 in tumor tissues (P<0.001)." (PMID 40703507, 2025). "ROC curves showed an AUC of 0.825 for CPLX1, indicating that it accurately distinguishes between tumor and normal control samples." (PMID 40703507, 2025). "In addition, we examined the expression of CPLX1, the proliferation-related marker Ki-67 and the metastasis-related markers Eca and Nca in subcutaneous tumor tissues of both groups using immunohistochemical methods." (PMID 40703507, 2025). "This showed significantly higher levels of CPLX1 in tumor tissues relative to the controls." (PMID 40703507, 2025). "In addition, higher levels of CPLX1 expression were found to be related to worse patient prognosis and more advanced clinical stages of the tumor." (PMID 40703507, 2025). "This study aims to elucidate the prognostic significance of CPLX1 in CRC, specifically its correlation with immunotherapy resistance and its association with ferroptosis, thereby contributing to a deeper understanding of tumor biology and therapeutic vulnerability." (PMID 40703507, 2025). "The results showed that knockdown of CPLX1 could effectively reduce the tumorigenicity of RKO cells and inhibit the proliferation of tumor cells." (PMID 40703507, 2025).
CPLX1 also shares sentences with these, for which no sentence is quoted: Alzheimer disease (2 papers); depression (2); neurological diseases (2); behavioral disorders (1); Behçet's disease (1); cortical atrophy (1); developmental and epileptic encephalopathy 63 (1); Dravet syndrome (1); Dystonia (1); glioblastoma (1); hyperlipidemia (1); lysosomal storage disease (1); movement disorder (1); myoclonic epilepsy (1); Seizure (1); Tremor (1); uterine corpus endometrial carcinoma (1).